ENSG00000252040
Synonyms: LOC124903808
Gene: Small nucleolar RNA gene on chromosome 16 (68,630,223 to 68,630,354, reverse strand). Ensembl gene ENSG00000252040.
Gene Ontology:
Biological process: RNA processing
Cellular component: nucleolus
Homologues: Paralogues in human: SCARNA18B (63% identical), SCARNA18 (61% identical).